TOP2A (DNA topoisomerase II alpha)
Description:
Key decatenating enzyme that alters DNA topology by binding to two double-stranded DNA molecules, generating a double-stranded break in one of the strands, passing the intact strand through the broken strand, and religating the broken strand. May play a role in regulating the period length of BMAL1 transcriptional oscillation (By similarity).
Synonyms: TOP2; TOP2alpha; TOPIIA; TP2A
Tractability: Small molecule: an approved drug acts on it; a structure with a bound ligand is known; a high-quality ligand is known; it has a high-quality binding pocket; it belongs to a druggable protein family. Antibody: a drug acting on it is in phase 2 or 3 trials. PROTAC: UniProt records ubiquitination sites on it; ubiquitination databases record sites on it; its protein half-life has been measured; a small molecule that binds it is known.
Target class: Isomerase; Enzyme
Safety:
Unwanted effects reported when the protein is acted on. In parentheses: how it was acted on, where the effect was seen, and who reports it.
neutropenia (source: ClinPGx)
Gene: Protein-coding gene on chromosome 17 (40,388,525 to 40,417,896, reverse strand). Ensembl gene ENSG00000131747.
Subcellular location: Cytoplasm; Nucleus, nucleoplasm; Nucleus; Nucleus, nucleolus
Subcellular location (Human Protein Atlas): Nucleoplasm; Nucleoli
Pathways (Reactome):
Cell Cycle: Transcription of E2F targets under negative control by DREAM complex
Metabolism of proteins: SUMOylation of DNA replication proteins
Gene Ontology:
Molecular function: ATP-dependent activity, acting on DNA; chromatin binding; DNA binding; DNA binding, bending; DNA topoisomerase type II (double strand cut, ATP-hydrolyzing) activity; magnesium ion binding; protein binding; protein heterodimerization activity; protein homodimerization activity; protein kinase C binding; RNA binding; ubiquitin binding; ATP binding
Biological process: apoptotic chromosome condensation; chromatin organization; chromosome segregation; DNA damage response; DNA topological change; positive regulation of apoptotic process; positive regulation of single stranded viral RNA replication via double stranded DNA intermediate; regulation of circadian rhythm; resolution of meiotic recombination intermediates; sister chromatid segregation; DNA metabolic process; female meiotic nuclear division
Cellular component: centriole; cytoplasm; DNA topoisomerase type II (double strand cut, ATP-hydrolyzing) complex; nuclear chromosome; nucleolus; nucleoplasm; nucleus; protein-containing complex; ribonucleoprotein complex; chromosome; chromosome, centromeric region; condensed chromosome
Genetic constraint (gnomAD): Loss-of-function variants: 50 observed, 150.05 expected, observed/expected ratio (o/e) 0.33, 90% interval 0.26 to 0.42. The upper end of that interval is the gene's LOEUF score, 0.42, which puts it in group 1 of 6, group 1 being the genes least tolerant of losing a copy. Missense variants: 1,072 observed, 1,623.1 expected, observed/expected ratio (o/e) 0.66, 90% interval 0.63 to 0.69. Synonymous variants: 492 observed, 546.6 expected, observed/expected ratio (o/e) 0.9, 90% interval 0.83 to 0.97.
Homologues: Orthologues: chimpanzee TOP2A (99% identical), macaque TOP2A (98% identical), pig TOP2A (94% identical), dog TOP2A (93% identical), rabbit TOP2A (93% identical), mouse Top2a (90% identical), rat Top2a (89% identical), guinea pig TOP2A (88% identical), tropical clawed frog top2a (72% identical), zebrafish top2a (68% identical). Paralogues in human: TOP2B (70% identical).
Diseases named in the same sentence as TOP2A in open-access papers:
TOP2A is named in the same sentence as 250 diseases in open-access papers, as found by Europe PMC text mining. Sharing a sentence is not in itself a finding about the gene and the disease. The quoted sentences say what the papers report.
breast carcinoma (213 papers, 2003 to 2026). "The GEPIA and cProSite databases were used to analyze the association between UBE2C and TOP2A, according to mRNA and protein abundance in breast cancer." (PMID 40729680, 2025). "High expression of TOP2A is currently believed to be associated with chemotherapy resistance in various malignancies, including breast cancer and colorectal cancer." (PMID 40487391, 2025). "TOP2A was found to be highly expressed in non-small cell lung cancer, hepatocellular carcinoma, and breast cancer and is associated with tumor proliferation and poor prognosis." (PMID 38012642, 2023). "We determined association of XBP1-gene signature (RRM2, CDC6 and TOP2A) with the outcome in breast cancer." (PMID 36997866, 2023). "TOP2A is directly associated with tumor cell proliferation and invasiveness in breast cancer, and expression has been reported to be amplified in TNBC patients with high-risk factors such as large tumor size, high-grade tumor, and lymph node infiltration." (PMID 37880313, 2023). "Several studies had earlier reported associations between a high expression of TOP2A and poor prognosis in breast cancer." (PMID 38137396, 2023). "Alterations in the TOP2A gene are associated with anthracycline adjuvant sensitivity in human breast cancer." (PMID 36531013, 2022). "This study provides novel insights into the biology of triple-negative PABC tumors suggesting that CNAs, particularly 8p loss and TOP2A loss, are involved in the development of breast cancer during pregnancy." (PMID 35792986, 2022). "The only publication that describes polymorphism of rs13695 TOP2A gene concerns breast cancer patients." (PMID 31797573, 2020). "We had a similar observation when analyzing changes in the topoisomerase II α gene (encoded by TOP2A) in breast cancers." (PMID 30995757, 2019). "In breast cancer, high expression of TOP2A is associated with low expression of estrogen receptor (ER) and high expression of Ki-67, and was proposed to be an important prognostic molecular indicator." (PMID 31816603, 2019). "TOP2A was a significant prognostic factor in predicting the breast cancer patient OS, and low expression of TOP2A was associated with a better clinical outcome." (PMID 31428132, 2019). "In breast cancer, TOP2A protein or gene expression is also associated with a poor prognosis; the prognostic value is emphasized in hormone receptor-positive disease." (PMID 29928479, 2018). "Because TOP2A amplified was strongly associated with HER2 positivity, the prognostic value of TOP2A amplified was examined using the log-rank test in HER2 positive breast cancer." (PMID 29928479, 2018). "In this study, the prognostic value of TOP2A amplified was evaluated in HER2 positive breast cancer because TOP2A amplified was shown to be strongly associated with HER2 positivity, as shown in previous studies." (PMID 29928479, 2018). "Additional evidence suggests that high levels of TOP2A expression is associated with increased sensitivity to doxorubicin in cervix and breast cancer cells." (PMID 28323900, 2017). "It has also reported that TOP2A was the well-known good prognostic marker in breast cancers, which was associated with a favorable response to anthracyclin-based therapy." (PMID 28969025, 2017). "In the present study, we developed a risk for recurrence score (RRS), based on mRNA expression of two proliferation markers (RACGAP1 and TOP2A), in high-risk early breast cancer patients and evaluated its ability to predict risk for relapse and death." (PMID 27695115, 2016).
breast carcinoma (continued). "In the present study, we sought to develop a risk for recurrence score (RRS) based on three proliferation markers, e.g. RACGAP1, TOP2A and Ki67, in high-risk early breast cancer patients and evaluate its ability to predict risk for relapse and death." (PMID 27695115, 2016). "We also performed in vivo ubiquitylation assays and examined the effect of RNF168 deficiency in human breast cancer cell lines on the level of TOP2α ubiquitylation." (PMID 27558965, 2016). "It has been reported that coamplification of HER2 and TOP2A in breast cancer is associated with sensitivity to anthracycline." (PMID 25695068, 2015). "HER2 and TOP2A gene status are assessed for diagnostic and research purposes in breast cancer with fluorescence in situ hybridization (FISH)." (PMID 25098819, 2014). "We have observed that TOP2A indeed appears among the top 50 genes in terms of its association with the attractor in breast cancer." (PMID 23468608, 2013). "In conclusion, this study confirms the favorable prognostic value of HER2/TOP2A co-amplification and the adverse prognostic value of high TOP2A mRNA expression extending it to the adjuvant treatment setting in early high-risk breast cancer." (PMID 22240029, 2012). "This study confirms the favorable prognostic value of HER2/TOP2A co-amplification and the adverse prognostic value of high TOP2A mRNA expression extending it to the adjuvant treatment setting in early high-risk breast cancer." (PMID 22240029, 2012). "In fact, this latter finding was the only contrasting point between the present study involving high-risk early breast cancer in comparison to low-risk early breast cancer, where TOP2A mRNA was unfavourably associated with metastasis-free survival." (PMID 22240029, 2012). "Co-amplification of HER2 and TOP2A was associated with favorable response to anthracycline-based therapy of locally advanced breast cancer." (PMID 23092535, 2012). "In breast cancer, TOP2A expression has been linked to cell proliferation and HER2 protein overexpression." (PMID 22016618, 2011). "The TOP2A deletion is associated with increased risk of BC recurrence and death from breast cancer in patient with ERBB2 amplified BC." (PMID 18702822, 2008). "Taken together, these results showed that inhibition of UBE2C could promote Parkin‐mediated K63‐linked ubiquitination of TOP2A to induce senescence and sensitize breast cancer cells to doxorubicin." (PMID 40729680, 2025). "Moreover, the inhibition of UBE2C promoted Parkin‐mediated K63‐linked ubiquitination of TOP2A, leading to its proteasomal degradation and thus sensitizing breast cancer cells to doxorubicin." (PMID 40729680, 2025). "All in all, UBE2C inhibition could promote Parkin‐mediated K63‐linked ubiquitination of TOP2A to induce senescence and increase doxorubicin sensitivity in breast cancer." (PMID 40729680, 2025). "For example, in breast cancer, high levels of TOP2A expression are associated with HER2-positive breast cancer and may promote tumor growth by regulating the HER2 signaling pathway." (PMID 41284119, 2025). "In breast cancer, TOP2A overexpression is associated with higher tumor grade and Ki67 index." (PMID 39727717, 2024). "Higher TOP2A expression was significantly associated with tumor size, poor grading, human epidermal growth factor receptor 2 expression, and positive lymph nodes in breast cancer." (PMID 36917092, 2023). "Moreover, in breast cancer, high TOP2A expression is associated with local recurrence after radiotherapy." (PMID 35912241, 2022). "For example, inhibition of DNA topoisomerase II alpha by doxorubicin may interrupt the efficient repair of DNA damage caused by cisplatin in EMT6 mouse mammary carcinoma or human glioblastoma cells." (PMID 33921230, 2021). "However, high expression of TOP2A protein seemed to be associated with poor prognosis only in luminal breast cancer." (PMID 29587760, 2018).
breast carcinoma (continued). "Moreover, TOP2A (gene of DNA topoisomerase 2-alpha) expression in breast cancer was associated with high proliferation and aggressive tumor subtypes and appears to be independent of its amplification status." (PMID 30176902, 2018). "Furthermore, HIDEEP reveals that doxorubicin directly targets TOP2A, one of breast cancer-causing genes, and dexamethasone has impacts on TOP2A through HEPs such as ANXA1 → SUMO3 → TOP2A and NR0B1 → UBC → TOP2A." (PMID 29192270, 2017). "For docetaxel, a well-established clinically anti-mitotic chemotherapy medication that works by interfering with cell division, the gene TOP2A, which encodes the key enzyme involved in DNA replication was proposed as the marker gene most relevant to docetaxel-resistance in breast cancer patients." (PMID 26824188, 2016). "TOP2A coamplification in HER2-amplified breast cancer might cause an increased sensitivity to TOP2A inhibitors by inducing the overexpression of the TOP2A protein." (PMID 25695068, 2015). "TOP2A gene amplification and, perhaps, topoisomerase II alpha (TopoIIa) protein overexpression may benefit high-risk breast cancer patients treated with anthracyclines." (PMID 23537287, 2013). "Importantly, we show here that the TOP2A index was associated with complete pathological response in breast cancer patients treated with an anthracycline containing chemotherapy regimen in the neoadjuvant setting." (PMID 22578285, 2012). "Furthermore, in locally advanced breast cancer, TOP2A levels in the primary tumor have been associated with greater tumor response to anthracycline therapy." (PMID 21785684, 2011). "TOP2A deletion is associated with poor prognosis in ERBB2-amplified breast carcinomas." (PMID 18702822, 2008). "The tumours with a TOP2A amplification contributed hardly to this difference, suggesting that TOP2A amplification is not the cause of the steep dose–response curve for anthracyclines in breast cancer." (PMID 17088909, 2006). "TOP2A mRNA expression is an independent prognostic factor in patients with (Estrogen Receptor) ER-positive breast cancer and could be useful in the assessment of breast cancer risk." (PMID 34249670, 2021). "Co-amplification of TOP2A and HER2 genes in breast cancer is associated with improved outcomes when treated with anthracyclines, highlighting the enzyme’s role as a predictive biomarker for chemotherapy efficacy." (PMID 40831931, 2025). "This study is the first to investigate the combined expression of fascin and TOP2A/CEP17 ratio in breast cancer." (PMID 40243780, 2025). "This inhibition also downregulated the expression of topoisomerase II‐ alpha (TOP2A), sensitizing breast cancer cells to doxorubicin and aggravating doxorubicin‐induced senescence." (PMID 40729680, 2025). "A five-gene SLE prognostic signature (RACGAP1, HMMR, TTK, TOP2A, and KIF15) effectively stratified breast cancer survival risk." (PMID 40567613, 2025). "Overexpression of TOP2A has been reported to predict poor survival in breast cancer, prostate cancer, hepatocellular carcinoma and colorectal cancer." (PMID 40831931, 2025). "UBE2C knockdown downregulated the expression of TOP2A and treatment with MG132 recovered the expression of TOP2A in breast cancer cells." (PMID 40729680, 2025). "Future prospective, multicenter studies with well-balanced cohorts would help assess the prognostic and predictive value of fascin and TOP2A alterations in breast cancer." (PMID 40243780, 2025). "Genomic analysis revealed that CASC3 is highly expressed in breast cancer with HER2/TOP2A co-amplification compared with HER2-amplified breast cancer." (PMID 40978141, 2025).
breast carcinoma (continued). "The small number of men (n = 4) reflects the 1% prevalence of male breast cancer; however, fascin and TOP2A expression variability in men remains uncertain." (PMID 40243780, 2025). "In the present study, UBE2C was identified for the first time as a novel regulator of TOP2A expression in breast cancer." (PMID 40729680, 2025). "Specifically, in breast cancer, TOP2A overexpression has been correlated with increased tumor grade and increased incidence of distant metastasis." (PMID 40732340, 2025). "Previous studies have shown that TOP2A is highly expressed in several types of cancers, including breast cancer and uroepithelial carcinoma, and serves as a biomarker for these cancers." (PMID 41284119, 2025). "This study investigated fascin and TOP2A expression in breast cancer and their relationship with clinical outcomes." (PMID 40243780, 2025). "Aberrations of chromosome 17q12-q22 have been reported in breast cancer and this locus incorporates the TOP2A gene along with HER2." (PMID 39888956, 2025). "For instance, in breast cancer, O-GlcNAcylation of TOP2A has been shown to enhance its catalytic activity, which in turn contributes to chemoresistance." (PMID 40290723, 2025). "It was recently demonstrated that TOP2A, particularly its O-GlcNAcylation, promotes malignant breast cancer progression and resistance to Adriamycin (Adm)." (PMID 39846632, 2024). "Analysis of Top2A, Top2B, and cyclin D1 expression in 2254 human breast cancer samples showed cyclin D1, and TOP2A co-expression was associated with ERα+ tumors." (PMID 38191593, 2024). "Other authors reported similar results: increased TOP2A expression is particularly evident in more aggressive subtypes of early breast cancer." (PMID 39727717, 2024). "Mechanistically, O-GlcNAcylation modulates interactions between TOP2A and cell cycle regulators, influences downstream gene expression, and contributes to breast cancer drug resistance." (PMID 38447797, 2024). "We next analysed the expression of RRM2, CDC6 and TOP2A in two breast cancer patient datasets pre- and post-endocrine treatment (GSE10281, GSE80077)." (PMID 36997866, 2023). "TOP2A is overexpressed in many human cancers including breast cancer, rendering this protein a widely used anti-cancer target." (PMID 37888205, 2023). "Previous studies have found that CENPF, MELK, PBK, TOP2A and NEK2 are upregulated in breast cancer and this is associated with a poor prognosis." (PMID 36776306, 2023). "Our results showing the increased expression of RRM2, CDC6 and TOP2A in XBP1-dependent manner provides a mechanism for their overexpression in breast cancers." (PMID 36997866, 2023). "TOP2A can also reportedly induce apoptosis in breast cancer through the caspase-3 signaling pathway." (PMID 37781045, 2023). "Recent studies suggested that TOP2A has potential applications in breast cancer detection and management." (PMID 37880313, 2023). "The weakening of the phosphatase and tensin homolog (PTEN)/AKT signal leads to a decrease in TOP2A expression in breast cancer, which in turn promotes apoptosis through the ATP/caspase 3 signaling pathway." (PMID 37818158, 2023). "In mice, the TOP2A gene was overexpressed in mouse mammary tumor cell lines M27 (mammary benign tumor cell line), M6 (mammary malignant tumor cell line), and M6C (mammary metastatic tumor cell line), with the M28 mammary cell line serving as a normal control." (PMID 37880313, 2023). "Our goal was to identify TOP2A- or DNMT1-enriched TECs that resembled our findings in the mouse mammary tumor models." (PMID 37055433, 2023). "Studies have shown that TOP2A is overexpressed in pancreatic cancer, breast cancer, and malignant peripheral schwannoma." (PMID 36233060, 2022). "A long-term clinical cohort study showed that high expression of TOP2A in breast cancer patients can be used as a marker for the application of anthracycline-containing chemotherapeutics.." (PMID 35873470, 2022).